UFM1 (ubiquitin fold modifier 1)
Description:
Ubiquitin-like modifier which can be covalently attached via an isopeptide bond to lysine residues of substrate proteins as a monomer or a lysine-linked polymer. The so-called ufmylation, requires the UFM1-activating E1 enzyme UBA5, the UFM1-conjugating E2 enzyme UFC1, and the UFM1-ligase E3 enzyme UFL1. Ufmylation is involved in various processes, such as ribosome recycling, response to DNA damage, transcription or reticulophagy (also called ER-phagy) induced in response to endoplasmic reticulum stress.
Synonyms: C13orf20; BM-002; bA131P10.1; HLD14
Tractability: Small molecule: a structure with a bound ligand is known. PROTAC: UniProt records ubiquitination sites on it; ubiquitination databases record sites on it; its protein half-life has been measured.
Gene: Protein-coding gene on chromosome 13 (38,349,826 to 38,363,619, forward strand). Ensembl gene ENSG00000120686.
Subcellular location: Nucleus; Cytoplasm
Gene Ontology:
Molecular function: protein binding
Biological process: brain development; negative regulation of protein import into nucleus; protein K69-linked ufmylation; protein ufmylation; regulation of intracellular estrogen receptor signaling pathway; response to endoplasmic reticulum stress; reticulophagy; negative regulation of apoptotic process
Cellular component: cytoplasm; nucleus; endoplasmic reticulum
Genetic constraint (gnomAD): Loss-of-function variants: 2 observed, 7.41 expected, observed/expected ratio (o/e) 0.27, 90% interval 0.11 to 0.85. That is too few expected variants to judge how well the gene tolerates losing a copy. Missense variants: 40 observed, 47.68 expected, observed/expected ratio (o/e) 0.84, 90% interval 0.65 to 1.09. Synonymous variants: 18 observed, 21.49 expected, observed/expected ratio (o/e) 0.84, 90% interval 0.58 to 1.24.
Gene-disease validity (ClinGen):
ClinGen rates the evidence that UFM1 causes each of these diseases.
leukodystrophy, hypomyelinating, 14 (autosomal recessive): Definitive.
Homologues: Orthologues: mouse Ufm1 (100% identical), pig UFM1 (100% identical), rabbit UFM1 (100% identical), guinea pig UFM1 (99% identical), rat Ufm1 (99% identical), zebrafish ufm1 (96% identical), tropical clawed frog ufm1 (93% identical), Caenorhabditis elegans ufm-1 (87% identical), Drosophila melanogaster Ufm1 (86% identical), dog UFM1 (80% identical), macaque UFM1 (80% identical).
Diseases named in the same sentence as UFM1 in open-access papers:
UFM1 is named in the same sentence as 70 diseases in open-access papers, as found by Europe PMC text mining. Sharing a sentence is not in itself a finding about the gene and the disease. The quoted sentences say what the papers report.
microcephaly (12 papers, 2018 to 2025). A congenital or acquired developmental disorder in which the circumference of the head is smaller than normal for the person's age and sex. "CNS-specific knockout of UFM1 in mice caused neonatal death accompanied by microcephaly and the apoptosis of specific neurons." (PMID 37947621, 2023). "Mutations of CYB5R3 and genes involved in the UFM1 system cause hereditary developmental disorders, and ufmylation-defective Cyb5r3 knock-in mice exhibit microcephaly." (PMID 36543799, 2022). "Biallelic mutations of UFM1 or UFC1 are also associated with microcephaly, global developmental delay, and seizures." (PMID 36543799, 2022). "Similar to the patients described here, UFM1 variants cause a disorder of severe intellectual disability, intractable epilepsy, microcephaly, and poor growth (leukodystrophy, hypomyelinating, 14, HLD14, OMIM 617899)." (PMID 33473208, 2021). "Here, we establish a locus for severe early-onset encephalopathy with progressive microcephaly based on two families, and map the phenotype to a novel homozygous UFM1 mutation." (PMID 29868776, 2018). "More recently, a homozygous UFM1 variant was proposed as a candidate aetiology of severe early-onset encephalopathy with progressive microcephaly." (PMID 29868776, 2018). "Moreover, a homozygous missense mutation in UFM1 (UFM1 p.R81C) has been observed in patients suffering from severe early-onset encephalopathy accompanied by progressive microcephaly." (PMID 40468360, 2025). "Genetic studies have revealed that variants of the human UBA5, UFC1, and UFM1 genes are associated with a number of neurodevelopmental diseases, including infantile-onset encephalopathy, autosomal recessive cerebellar ataxia, and microcephaly." (PMID 37947621, 2023). "Mutations in the UFM1 gene are associated with Hypomyelinating leukodystrophy type 14, presenting with global developmental delay, failure to thrive, progressive microcephaly, refractive epilepsy, and hypomyelination, with atrophy of the basal ganglia and cerebellum phenotypes." (PMID 34573312, 2021). "For example, the CNS-specific conditional knockout of UFM1 in mice results in neonatal death, accompanied by microcephaly and apoptosis in specific neurons, illustrating that the UFM1 system is essential for CNS development and function." (PMID 39846712, 2025). "Mutations in UFM1, as well as in its specific E1 enzyme UBA5 and E2 enzyme UFC1, have been genetically linked to microcephaly." (PMID 39085203, 2024). "Biallelic mutations in the UBA5 (ubiquitin-activating enzyme of UFM1) gene were recently seen to cause SCAR24 and early onset encephalopathy with intellectual deficiency, microcephaly, movement disorders, and epilepsy." (PMID 33917666, 2021). "Since the UFM1 cascade regulates cell cycle progression at the entry into mitosis, certain chemicals or drugs targeting CDK1 could be used to address microcephaly phenotypes, as observed in the case of HLD14." (PMID 39846712, 2025). "The clinical phenotype of previously reported patients with UBA5 and UFM1 mutations are similar to our UFM1 and UFC1 patients, particularly regarding failure to thrive, short stature, microcephaly, GDD, seizures, basal ganglia abnormality, delayed CNS myelination, and cerebellar hypoplasia." (PMID 29868776, 2018). "Moreover, mutations in UFM1 and UFC1 were shown to cause neurologic disease with global developmental delay, progressive microcephaly, short stature and refractory epilepsy, a phenotype highly reminiscent of that observed in individuals with UBA5-related epileptic encephalopathy." (PMID 38046095, 2023). "In a Drosophila model, the disruption of genes in the UFM1 cascade, including UFC1, greatly decreases the number of neuroblasts, resulting in the smaller brain size observed in microcephaly." (PMID 39846712, 2025).
breast carcinoma (9 papers, 2015 to 2025). "UFM1 is a potential marker protein that induces DNA double-strand breaks response, and is associated with breast cancer progression." (PMID 35121801, 2022). "Several studies have reported the association of UFM1 with prognosis in GC, HCC, and breast cancer patients." (PMID 37980168, 2023). "It was previously found that UFL1 interaction with UFM1 is critical for the UFMylation of activating signal cointegrator 1 under estrogen to inhibit breast cancer growth." (PMID 32655766, 2020). "Although UFM1 has been reported to be involved in the progression of breast cancer, its role in gastric cancer is still unclear." (PMID 31533855, 2019). "Here, we discuss the mechanistic connection between ASC1 modification by UFM1 and ERα transactivation, and highlight how the interplay of these processes is involved in development of breast cancer." (PMID 25852645, 2015). "We also discuss potential use of UFM1-conjugating system as therapeutic targets against not only breast cancer but also other nuclear receptor-mediated cancers." (PMID 25852645, 2015). "Thus, UFBP1, like UFL1, plays two opposite roles as a tumor suppressor by inhibiting NF-κB signaling and as a tumor promoter by serving as a cofactor of the UFM1-conjugating system for ASC1 in development of breast cancer." (PMID 25852645, 2015). "Metformin can inhibit the expression of the ubiquitin-like protein UFM1, which in turn suppresses the UFMylation of SLC7A11, leading to its reduced expression and induction of ferroptosis in breast cancer cells, thereby inhibiting cancer progression." (PMID 40374601, 2025). "Previous studies confirmed that the changes in UFM1 expression were related to the progression of gastric cancer (GC), hepatocellular carcinoma (HCC), and breast cancer." (PMID 37980168, 2023). "To clarify the role of UFM1 in ferroptosis regulation by metformin, we first detected the expression of SLC7A11 and UFM1 in different breast cancer cell lines." (PMID 34162423, 2021). "Despite extensive research regarding other proteins involved in the UFM1 system, as well as the importance of UFL1 in mastitis and breast cancer, our knowledge of UFL1 function in the mammary gland requires further elucidation." (PMID 32655766, 2020). "In this review, we will provide an overview on current and emerging roles of the UFM1 system, with a focus on ASC1 ufmylation in regulation of breast cancer development." (PMID 25852645, 2015). "Next, utilizing publicly available databases, our bioinformatics analysis showed that there was a significant negative correlation between the expression of SLC7A11 and the prognosis of breast cancer patients, but not UFM1." (PMID 34162423, 2021). "Thus, each component of the UFM1-conjugating machinery and UFSP2 that reverses ufmylation process could be potential targets for development of drug against ERα-positive breast cancer." (PMID 25852645, 2015).
gastric cancer (8 papers, 2019 to 2024). A primary or metastatic malignant neoplasm involving the stomach. "UFM1 expression was decreased at both protein level and mRNA level in gastric cancer tissues, which was associated with low 5-year survival rate in patients with gastric cancer." (PMID 39247188, 2024). "The association between the UFM1 expression and the outcomes of gastric cancer patients who had surgery was determined by Lin and coworkers." (PMID 39247188, 2024). "The association of different CDK5RAP3 and UFM1 expression levels in gastric cancer tissues with clinicopathological factors." (PMID 36387125, 2022). "The association of CDK5RAP3 and UFM1 expression in gastric cancer tissues with clinicopathological factors." (PMID 36387125, 2022). "In univariate analysis, low CDK5RAP3 expression was linked to a poor prognosis, and high UFM1 expression was linked to a better survival rate in gastric cancer patients, indicating that both CDK5RAP3 and UFM1 play a tumour suppressor role in gastric cancer." (PMID 36387125, 2022). "The UFM1 conjugation system is also implicated in the pathogenesis of gastric cancer." (PMID 35884562, 2022). "Low expression of UFM1 and CDK5RAP3 was associated with poor prognosis, which was independent predictor to predict overall survival of gastric cancer patients." (PMID 39247188, 2024). "Upregulation of UFM1 inhibited migration and invasion abilities in gastric cancer cells, while downregulation of UFM1 exhibited the opposite functions." (PMID 39247188, 2024). "Mechanistically, UFM1 suppresses gastric cancer invasion and metastasis by using ubiquitination to increase PDK1 degradation by negatively regulating PI3K/AKT signaling." (PMID 37947621, 2023). "The overexpression of UFM1 inhibited the oncogenic properties of gastric cancer both in vivo and in vitro, while the knockdown of UFM1 yielded the opposite results." (PMID 35884562, 2022). "In comparison to the conventional TNM staging’s forecast accuracy, combining CDK5RAP3 and UFM1 expression with TNM greatly improved the accuracy of predicting gastric cancer patient survival." (PMID 36387125, 2022). "It was suggested that UFM1 was positively correlated with CDK5RAP3 and its low expression was associated with poorer prognosis of gastric cancer." (PMID 36387125, 2022). "IHC staining score was used to analyse CDK5RAP3 and UFM1 protein expression in paraffin-embedded gastric cancer samples from 124 patients." (PMID 36387125, 2022). "In a study, the level of UFM1 was significantly decreased in gastric cancer tissue compared with the normal control." (PMID 35884562, 2022). "The relationship between the CDK5RAP3 and UFM1 expression and the prolonged outcomes of patients who underwent gastric cancer (GC) surgery was investigated." (PMID 36387125, 2022). "Analysis of factors associated with the expression of CDK5RAP3 and UFM1 in gastric cancer tissues showed that the CDK5RAP3 and UFM1 expression significantly correlated with BMI, lymph node metastasis, depth of invasion and pathological TNM stage." (PMID 36387125, 2022). "To date, few studies have investigated the combined expression levels of CDK5RAP3 and UFM1 and its prognostic significance in gastric cancer." (PMID 36387125, 2022). "This study aims to clarify the role and potential molecular mechanisms of UFM1 in the invasion and metastasis of gastric cancer." (PMID 31533855, 2019). "Compared with the corresponding adjacent tissues, the transcription level and protein expression level of UFM1 in gastric cancer tissues were significantly downregulated (P < 0.05)." (PMID 31533855, 2019). "To further explore the possible mechanism by which UFM1 regulates the metastatic potential and EMT in gastric cancer, we used co-immunoprecipitation to identify possible binding proteins for UFM1." (PMID 31533855, 2019). "The 5-year survival rate of gastric cancer patients with low UFM1 expression was significantly lower than the patients with high UFM1 expression (42.1% vs 63.0%, P < 0.05)." (PMID 31533855, 2019).
gastric cancer (continued). "Our previous study has shown that the expression level of UFM1 is significantly down regulated in gastric cancer tissues than in adjacent tissues." (PMID 31533855, 2019). "We observed that knockdown of UFM1 resulted in a decrease in tight junctions between cells and a morphological change in epithelial mesenchymal transition in gastric cancer cells." (PMID 31533855, 2019). "The results also showed that patients with gastric cancer with high expression of UFM1 had a better prognosis." (PMID 31533855, 2019). "We also constructed a subcutaneous tumor model in nude mice to evaluate the effect of UFM1 on the tumorigenic ability of gastric cancer cells in vivo." (PMID 31533855, 2019). "UFM1 suppresses the invasion and metastasis of gastric cancer by increasing the ubiquitination of PDK1 through negatively regulating PI3K/AKT signaling." (PMID 31533855, 2019). "Among the 120 patients with primary gastric cancer, the UFM1 score was low in 91 cases (75.8%) and high in only 26 cases (24.2%), and the downregulation of UFM1 expression was closely related to the more advanced TNM stage." (PMID 31533855, 2019). "We tested the expression level of UFM1 protein in different gastric cancer cell lines and found that AGS was at a medium level." (PMID 31533855, 2019). "The effects of UFM1 on the invasion and migration of gastric cancer cells were determined by the wound and trans-well assays, and the effect of UFM1 on subcutaneous tumor formation was verified in nude mice." (PMID 31533855, 2019). "Western blot showed that E-cadherin expression was decreased and of N-cadherin, Vimentin, and Snail were increased in gastric cancer cells, which downregulated UFM1 expression." (PMID 31533855, 2019). "The expression level of UFM1 can improve the poor prognosis of PDK1 in patients with gastric cancer." (PMID 31533855, 2019). "By qPCR analysis, we found that the transcription level of UFM1 was downregulated in gastric cancer tissues (n = 93, 80.2%) compared with the corresponding adjacent tissues." (PMID 31533855, 2019). "The results showed that the expression of UFM1 was significantly higher in adjacent tissues than in the corresponding gastric cancer tissues." (PMID 31533855, 2019). "The results showed that the transcription level of UFM1 in gastric cancer tissues was downregulated based on the data uploaded by Wang, consistent with the results of our present study." (PMID 31533855, 2019). "UFM1 had an inhibitory effect on the tumorigenicity, invasion and migration of gastric cancer cells." (PMID 31533855, 2019). "To explore the mechanism of UFM1 on the invasion and metastasis of gastric cancer, we screened 10 differentially regulated signaling molecules in AGS (downregulated UFM1 expression levels) using the human phosphokinase microarray." (PMID 31533855, 2019). "Moreover, the expression of UFM1 was determined in cancerous and paracancerous gastric cancer tissues." (PMID 39247188, 2024). "Thereby, we considered that CDK5RAP3 and UFM1 may play a coordinated role in inhibiting the gastric cancer invasion and metastasis." (PMID 36387125, 2022). "Interestingly, while our data show that prevention of ufmylation in HeLa cells reduces the ability of the cells to migrate, in gastric cancer cells, downregulation of UFM1 expression enhances the migration and invasion of these cells." (PMID 35806453, 2022). "Therefore, combination of the CDK5RAP3 and UFM1 expression can improve the capacity to forecast the survival outcomes of patients with gastric cancer." (PMID 36387125, 2022). "Additionally, we found that the functions of CDK5RAP3 and UFM1 in gastric cancer were positively correlated." (PMID 36387125, 2022). "Gastric cancer patients with low expression of UFM1 presented a poor prognosis." (PMID 31533855, 2019). "Furthermore, we found that the inhibitory effect of UFM1 on gastric cancer cell EMT was also prevented when PDK1 was knocked down." (PMID 31533855, 2019).